GIHCG (GIHCG inhibitor of miR-200b/200a/429 expression)
Synonyms: lncRNA-GIHCG
Gene: Long non-coding RNA gene on chromosome 12 (57,930,084 to 57,942,198, reverse strand). Ensembl gene ENSG00000257698.
Diseases named in the same sentence as GIHCG in open-access papers:
GIHCG is named in the same sentence as 18 diseases in open-access papers, as found by Europe PMC text mining. Sharing a sentence is not in itself a finding about the gene and the disease. The quoted sentences say what the papers report.
hepatocellular carcinoma (6 papers, 2021 to 2025). A malignant tumor that arises from hepatocytes. "This indicates that LINC00685 and GIHCG have high diagnostic values for hepatocellular carcinoma patients." (PMID 40792280, 2025). "GIHCG belongs to a family of non-coding RNA (ncRNA) and has been associated with prognosis in hepatocellular carcinoma and colorectal cancer." (PMID 34320000, 2021). "GIHCG was found to be upregulated in several cancer types, including hepatocellular carcinoma and cervical and renal carcinoma, and showed a role in proliferation and cell migration regulation." (PMID 38612674, 2024). "The lncRNA GIHCG (GIHCG Inhibitor of MiR-200b/200a/429 Expression) promotes the proliferation and metastasis of hepatoma cells by increasing histone H3K27 methylation in the promoter region of miR-200b/a/429, thereby silencing the expression of miR-200b/a/429." (PMID 38334963, 2024). "In previous studies, GIHCG was found to be highly expressed in a variety of tumors and to promote the development of hepatocellular carcinoma, esophageal carcinoma, renal cell carcinoma and other tumors through different pathways." (PMID 37978247, 2023).
gastric cancer (4 papers, 2019 to 2025). A primary or metastatic malignant neoplasm involving the stomach. "Studies have shown that lnc-GIHCG overexpression increases the proliferation and migration of gastric cancer cells by upregulating TLE1 expression through the adsorption of miR-1281." (PMID 35528617, 2022). "Hsa-miR-1281 was reported to be negatively regulated by linc-GIHCG in gastric cancer and breast cancer." (PMID 34912844, 2021). "Notably, in gastric cancer cells, the sequestration of miR-1322 by long non-coding RNA (lncRNA) GIHCG has been shown to enhance proliferation and migration." (PMID 40302808, 2025). "In validating experiments, we examined expression levels of GIHCG and SPINT1-AS1 in seven types of cancer cell lines (thyroid cancer, pancreatic cancer, liver cancer, melanoma, gastric cancer, breast cancer, and colorectal cancer) and Lapatinib IC50 of the same cancer cell lines." (PMID 30842786, 2019).
esophageal carcinoma (2 papers, 2023 to 2025). A primary or metastatic malignant neoplasm involving the esophagus. "In oesophageal cancer, the long noncoding RNA (lncRNA) GIHCG is significantly expressed." (PMID 40396170, 2025). "GIHCG inhibits miR-29b-3p, and this leads to increased ANO1 expression and promotes proliferation and invasion by oesophageal cancer cells." (PMID 40396170, 2025).
renal carcinoma (2 papers, 2019 to 2024). A carcinoma arising from the epithelium of the renal parenchyma or the renal pelvis. "GIHCG is also involved in promoting cancer proliferation and migration in tongue and renal cancers." (PMID 30842786, 2019).
renal cell carcinoma (2 papers, 2022 to 2023). "Higher levels of GIHCG as well as ARSR (for “activated in RCC with sunitinib resistance”) were also reported in the circulation of renal cell carcinoma patients." (PMID 35729321, 2022).
cervical cancer (1 paper, 2022). A primary or metastatic malignant neoplasm involving the cervix. "lncRNA GIHCG, highly expressed in cervical cancer, can distinguish cervical cancer patients from healthy controls with a sensitivity and specificity of 88.75 and 87.50%, respectively, making it a possible diagnostic biomarker." (PMID 36144454, 2022).
liver cancer (1 paper, 2019). An epithelial or non-epithelial malignant neoplasm that arises from the liver. "As the inhibitor of miR-200b/200a/429, LncRNA GIHCG was shown effectively promoting the progression of liver cancer through inducing methylation of miR-200b/200a/429 promoter." (PMID 30842786, 2019).
multiple myeloma (1 paper, 2021). "Because GIHCG inhibits a cluster of miRNA which play important roles in regulating the expression of a number of genes, functional studies are required to expand the relative effects of GIHCG in multiple myeloma." (PMID 34320000, 2021).
ovarian carcinoma (1 paper, 2020). A malignant neoplasm originating from the surface ovarian epithelium. "By searching related literature and databases, about 30% lncRNAs have been verified to play roles in the regulation of proliferation, invasion, and migration of ovarian cancer cells, including ZFAS1, SNHG1, GAS5, EMX20S, GIHCG, TP53TG1, EPB41L4A-AS1, SNHG8, SNHG6, and HCP5." (PMID 33519912, 2020).
cancer (7 papers, 2019 to 2024). A tumor composed of atypical neoplastic, often pleomorphic cells that invade other tissues. "In further experiments, GIHCG knockdown enhanced cancer cell susceptibility to Lapatinib, while high level of SPINT1-AS1 was a sensitive biomarker of NCI-N87 and MCF7 cancer cells to Lapatinib." (PMID 30842786, 2019). "Aberrant GIHCG-mediated miRNAs expression has also been shown to regulate the development and progression of different types of cancer." (PMID 36760365, 2023). "Other studies have revealed the role of GIHCG in key biological processes such as cell proliferation and cell migration in primary tumors and cancer cells." (PMID 34320000, 2021). "In this study, we analyzed the lncRNAs of whole-genome datasets of CCLE after treatment with Lapatinib on pan-cancer cell lines, and proposed crucial lncRNAs GIHCG and SPINT1-AS1 involved in regulating Lapatinib sensitivity." (PMID 30842786, 2019). "Although the role of lncRNAs in cancer progression and Lapatinib resistance have been reported in other studies, this is the first study that proved that lncRNAs GIHCG and SPINT1-AS1 are involved in regulating therapeutic sensitivity to Lapatinib." (PMID 30842786, 2019). "After knocking-down expression levels of GIHCG and SPINT1-AS1 by small interfering RNAs, Lapatinib IC50, and inhibitory rate of cancer cells were detected." (PMID 30842786, 2019). "By subsequent experimental study, lncRNAs GIHCG and SPINT1-AS1 were firstly identified as crucial lncRNAs in regulating Lapatinib resistance or sensitivity in epithelium-derived cancer cell lines." (PMID 30842786, 2019). "Correlation analysis showed that SPINT1-AS1 (R = −0.715, P < 0.001) and GIHCG (R = 0.557, P = 0.013) were correlated with the IC50 of epithelium-derived cancer cells." (PMID 30842786, 2019). "Of those, GIHCG and SPINT1-AS1 were only differentially expressed in epithelial derived cancers." (PMID 30842786, 2019). "Knocking-down of GIHCG could significantly enhance the sensitivity to Lapatinib in MCF7 and BxPC3 cancer cell lines, while down-regulation of SPINT1-AS1 could promote resistance to Lapatinib in NCI-N87 and MCF7 cancer cell lines." (PMID 30842786, 2019). "However, there is no study $om whether or not GIHCG could regulate Lapatinib drug sensitivity in cancers." (PMID 30842786, 2019). "Higher expressing level of SPINT1-AS1 was found in epithelium-derived cancer cells, and higher expressing levels of MAGI2-AS3 and GIHCG were observed in the non-epithelium group." (PMID 30842786, 2019). "Suppression of GIHCG in Lapatinib resistant cancer cell lines NCIH-747 and BxPC3 could induce up-regulation of SPINT1-AS1 (P < 0.05), while knockdown of SPINT1-AS1 did not change the expression level of GIHCG (P > 0.05)." (PMID 30842786, 2019).
tumor (6 papers, 2017 to 2025). "Moreover, there is a significant association between elevated levels of GIHCG and larger tumour size, microvascular invasion, advanced Barcelona Clinic Liver Cancer (BCLC) stage, and unfavourable survival outcomes among HCC patients." (PMID 40387409, 2025). "GIHCG knockdown suppresses tumour growth by reducing the direct binding of GIHCG to miR-29b-3p and inhibiting ANO1 production." (PMID 40396170, 2025). "Furthermore, GIHCG enhances xenograft tumour growth and metastatic potential in vivo." (PMID 40387409, 2025). "Then, we investigated the expression of these lncRNAs in normal and tumor tissues and found that the expression of AP003555.1, AF241728.2 and AC018761.2 was increased in tumors, while the expression of GIHCG was increased in normal tissues." (PMID 37978247, 2023). "In addition, lincRNA-p21 has been described as a tumor suppressor, while HOTAIR, MALAT-1, H19, PVT1, ANRIL, and GIHCG, have been characterized as oncogenic lncRNAs." (PMID 36360316, 2022). "GIHCG is overexpressed in RCC tissue as compared to healthy adjacent tissue and is also elevated in the serum of RCC patients, showing a highly significant correlation with tumor tissue expression levels." (PMID 33042985, 2020).
GIHCG also shares sentences with these, for which no sentence is quoted: breast carcinoma (2 papers); colorectal cancer (2); glioma (1); lung carcinoma (1); melanoma (1); pancreatic cancer (1); thyroid cancer (1).